CD34 (CD34 molecule)
Diseases named in the same sentence as CD34 in open-access papers (continued):
Sharing a sentence is not in itself a finding about the gene and the disease.
Cirrhosis (18 papers, 2014 to 2025). A chronic disorder of the liver in which liver tissue becomes scarred and is partially replaced by regenerative nodules and fibrotic tissue resulting in loss of liver function. "Histological evaluation with H&E, Masson’s trichome, and reticulin staining confirmed the presence of cirrhosis, while CD34 IHC indicated neovascularization associated with early malignant transformation." (PMID 41377976, 2025). "Accordingly, CD34 has been associated with capillarization of LSECs in a mouse model of cirrhosis." (PMID 36842152, 2023). "The rapid regression of CD34 staining observed in the present study contrasts with data obtained in patients with hepatitis C virus-related cirrhosis where CD34 staining remained unchanged 5 years after sustained virological response." (PMID 40486133, 2025). "Recently, given the increasing number of patients with MASH-derived cirrhosis, we evaluated the efficacy of CD34-positive cell transplantation in a murine MASH model." (PMID 40136677, 2025). "Additional analysis related to the primary endpoint in the CD34+ cell group showed CP score and class improvement in 5 of the 10 patients (50%) and improvement from decompensated to compensated cirrhosis in 4 (40%) at 24 weeks post-enrollment." (PMID 38737403, 2024). "As shown by CD34 immunostaining, sinusoidal capillarization was uncommon in cirrhosis and gradually increased from LGDN to HGDN, with the highest levels in HCC." (PMID 37046429, 2023). "Total CD34 expression was significantly increased in cases with cirrhosis compared to cases with stage 0–1 fibrosis (p = 0.0003), and in cases with stage 2–3 fibrosis compared to cases with stage 0–1 fibrosis (p = 0.042)." (PMID 35552548, 2022). "In comparison, 1 of 14 controls with primary liver cancer in cirrhosis had CD34 positivity in the background liver suggestive of generalized sinusoidal capillarization." (PMID 33639984, 2021). "Some studies have reported that G-CSF stimulates proliferation of hepatocytes in patients with alcoholic AH, cirrhosis, and liver failure, by mobilizing CD34-positive stem cells to the liver." (PMID 30577864, 2018). "•CD34+ cell therapy can avoid cirrhosis progression and boost liver reserve function." (PMID 38737403, 2024). "Furthermore, a subgroup analysis of patients with SVR showed a marked improvement in CP scores in the CD34+ cell group, with four of the eight patients improving from decompensated to compensated cirrhosis." (PMID 38737403, 2024). "The expression of CD34 increased gradually with cirrhosis, carcinogenesis, and metastasis." (PMID 37234705, 2023). "Lastly, CD34 expression on liver sinusoidal endothelial cells is linked to chronic liver inflammation and thought to play a role in the pathogenesis of HCC from underlying cirrhosis." (PMID 32228601, 2020). "Another important finding in this study was higher MVD-CD105 scores in RN compared with DN and HCC, demonstrating CD105 expression decreases gradually from cirrhosis to DN to small HCC, opposite to CD34 expression." (PMID 24507660, 2014). "Importantly, 4 out of 10 patients in the CD34+ cell group exhibited an improvement from decompensated to compensated cirrhosis, whereas all patients in the SOC group remained in decompensated cirrhosis." (PMID 38737403, 2024). "CD34 expression was not significantly different in cases with stage 2–3 fibrosis compared to cases with cirrhosis (p = 0.13)." (PMID 35552548, 2022). "Moreover, four of the eight patients (50%) in the CD34+ cell group exhibited an improvement from decompensated to compensated cirrhosis, while all patients in the SOC group remained in the decompensated stage of cirrhosis." (PMID 38737403, 2024). "The lack of difference in CD34 expression between cases with stage 2–3 fibrosis and cases with cirrhosis supports our hypothesis that many resected HCC patients with stage 2–3 fibrosis may be under-staged by routine histology alone due to fibrosis regression." (PMID 35552548, 2022).
Thrombocytopenia (18 papers, 2007 to 2025). A reduction in the number of circulating thrombocytes. "CD34 selected stem cell boost (SCB) has also been used for patients with insufficient engraftment including severe thrombocytopenia." (PMID 35268455, 2022). "Translating these results into clinical practice may lead to implementing a higher target dose of CD34‐positive cells required for HSCT among those with baseline moderate–severe thrombocytopenia." (PMID 41278511, 2025). "Transplantation of donor-derived CD34+-selected stem cell boost and pharmacological therapy with TPO-RA are under investigation as other options for managing prolonged thrombocytopenia and PGF after alloHCT." (PMID 36817464, 2023). "Furthermore, we observed an upregulation of DACH1 during in vitro differentiation of CD34–megakaryocytes and downregulation of DACH1 in patients with thrombocytopenia." (PMID 38542074, 2024). "To analyze whether the thrombocytopenia observed in AHF patients could be the result of altered megakaryopoiesis, we used an in vitro model of human CD34+ cells stimulated with thrombopoietin (TPO)." (PMID 20419155, 2010).
Cerebral ischemia (17 papers, 2007 to 2025). Restriction of arterial blood supply to the brain associated with insufficient oxygenation to support the metabolic requirements of the tissue. "Mechanistically, TFDM upregulated the expression of VEGF, VEGFR2, and CD34 in the ischemic penumbra of cerebral ischemia-reperfusion injured rats post‐injury." (PMID 41245636, 2025). "In this review, the authors summarized the preclinical and clinical evidence from over 700 patients in clinical trials of CD34+ cell therapy for ischemic events such as limb ischemia, myocardial ischemia, and cerebral ischemia." (PMID 36660500, 2022). "Immunohistochemistry also showed that l-borneol can increase the number of CD34 positive cells, further verifying that l-borneol can play a neuroprotective effect by promoting angiogenesis after cerebral ischemia injury." (PMID 33746762, 2021). "To investigate the microscopic structural changes of NVU, we determined the expression changes of NVU markers, including NeuN (neuronal marker), GFAP (glial cell marker), and CD34 (vascular endothelial cell maker) on the 14th day after cerebral ischemia." (PMID 27391841, 2016). "In an anesthetized rat model of heatstroke, CD34+ cell therapy significantly attenuates arterial hypotension, intracranial hypertension, cerebral ischemia, hypoxia, and injury, and TNF-α overproduction during heatstroke." (PMID 24804231, 2014). "Intravenous injection of CD34+ cells 48 hrs after experimental brain ischemia reduced lesion size, enhanced angiogenesis, and neurogenesis, and improved functional outcome." (PMID 21887230, 2011). "Cord blood CD34+ cells are known to be potent angiogenic stimulators, having demonstrated positive effects in not only peripheral ischemia, but also in models of cerebral ischemia." (PMID 17597540, 2007). "The importance of EPCs and angiogenesis on neurogenic responses is also supported by the finding that systemic administration of human cord blood-derived CD34+ cells can enhance neurogenesis via upregulated angiogenic responses in a mouse model of cerebral ischemia." (PMID 26407349, 2015). "WBH mice treated with CD34+ cells showed significant improvement of cerebral ischemia and hypoxia." (PMID 24804231, 2014). "From days 1–14 after cerebral ischemia reperfusion in rats, compared with the sham group, the expression levels of VEGF, VEGFR2, and CD34 proteins in the ischemic penumbra of both the I/R group and the I/R + TFDM group were significantly increased." (PMID 41245636, 2025). "The results showed that at different time points after cerebral ischemia reperfusion surgery, the number of VEGF-, VEGFR2-, and CD34-positive cells in both the I/R group and the I/R + TFDM group was significantly higher than that in the sham group." (PMID 41245636, 2025). "It is considered currently that CD34 + EPC-labeled EPCs have stronger proangiogenic ability than other surface marker-type EPCs and have been widely used in the study of revascularization after cerebral ischemia." (PMID 30622670, 2018). "Based on the links of brain ischemia-induced PACAP38 expression and PACAP38/PAC1 signaling in CD34+ BMDCs trafficking, we hypothesized PACAP38/PAC1 signaling is critical pathway involved in brain ischemia-mediated recruitment of BMDCs to the vascular niche." (PMID 25523790, 2015). "Western blotting analysis showed that cerebral ischemia led to a significantly decreased expression of CD34 in the peri-infarct area of SE mice (P<0.01), but had no significantly effects on the expression of CD34 in the peri-infarct area of EE mice." (PMID 28845299, 2017). "On the other hand, over expressed miR-210 contributes to angiogenesis after cerebral ischemia by activating the Notch signaling pathway, while miR-210 inhibitor abrogates and 210 mimic recapitulates the pro-angiogenic effects by VEGF treatment in post-expansion CD34+ cells." (PMID 24586608, 2014).
ganglioglioma (17 papers, 2011 to 2025). A well differentiated, slow growing neuroepithelial neoplasm composed of neoplastic, mature ganglion cells and neoplastic glial cells. "We used these high resolution results to deconvolute clinically-annotated transcriptomic data, confirming that CD34+ cell-associated gene programs associate with gangliogliomas compared to other glial brain tumors." (PMID 36966348, 2023). "The aim of the study was to evaluate the clinicopathological features, as well as the surgical prognosis, of epilepsy-associated gangliogliomas (GG) with CD34 expression and BRAFV600E mutation." (PMID 36910263, 2023). "In another study, the BRAF V600E mutation was found to be significantly associated with the expression of CD34 in 38/93 (40,8%) of ganglioglioma, confirming the quality of CD34 immunoreactivity as surrogate marker for GG and PXA." (PMID 32151273, 2020). "Furthermore, case 6 showed an extravascular expression of CD34, a marker consistently expressed in 70–80 % of gangliogliomas, especially those variants emerging from temporal lobe." (PMID 26671581, 2015). "Many pediatric low grade gliomas such as gangliogliomas contain tumor cells that express CD34, (an endothelial and hematopoietic stem cell marker but also) a transient marker of neuroectodermal neural precursor cells during neural development." (PMID 36966348, 2023). "Our data suggests such a mechanism for ganglioglioma tumorigenesis with CD34+ glioneuronal tumor cells as the tumor stem cells." (PMID 36966348, 2023). "Gangliogliomas are often characterized by a rare population of immature astrocyte-appearing cells expressing CD34, a marker expressed in the neuroectoderm (neural precursor cells) during embryogenesis." (PMID 36966348, 2023). "Together, these deep transcriptomic approaches characterized a ganglioglioma cellular hierarchy—confirming CD34+ neuroectoderm-like tumor precursor cells, controlling transcription programs, cell signaling, and associated immune cell states." (PMID 36966348, 2023). "Analysis of our neoplastic-appearing ganglioglioma nuclei in this manner assigned cluster 6 nuclei or CD34+ nuclei (and particularly cluster 6, CD34+ nuclei) the earliest pseudotimes." (PMID 36966348, 2023). "Meanwhile, CD34 is consistently expressed in 70-80% and BRAF V600E mutation occur in 20-60% of investigated cases of gangliogliomas." (PMID 35370935, 2022). "CD34 expression is a common attribute of pediatric gangliogliomas, pleomorphic xanthoastrocytomas, some dysembryoplastic neuroepithelial tumors, glioneuronal microhamartomas, and some cortical dysplasias." (PMID 29701169, 2018). "Specifically, expression of CD34 is a common attribute of pediatric gangliogliomas and PXAs, having also been recorded by some observers in the setting of DNET." (PMID 27812792, 2017). "Although more common in gangliogliomas, both tumor types may exhibit the BRAF V600E mutation, CD34 positivity, and associated features such as eosinophilic granular bodies, Rosenthal fibers, and lymphocytic infiltration." (PMID 39941264, 2025). "Hence, analysis of cell markers identified the majority of ganglioglioma cells as neoplastic-appearing with a rare CD34-rich population possibly representing tumor neuroectoderm neural precursor cell-like stem cells." (PMID 36966348, 2023). "Such CD34+ cells have previously been hypothesized to represent ganglioglioma tumor precursor/stem cells, but their transcriptomic profile and location in the tumor cell hierarchy was not previously well understood." (PMID 36966348, 2023). "Co-expression of CD34, PAX6, SOX2, and MSI1 (after stringent counter selection against vascular cells using PECAM1, VWF, DCN, and COL1A2), was particularly strongly associated with ganglioglioma neoplastic cell stemness." (PMID 36966348, 2023).
ganglioglioma (continued). "Therefore, the combination of CD34 positivity and BRAF V600E mutation we report raises ganglioglioma, pleomorphic xanthoastrocytoma, and dysembryoplastic neuroepithelial tumor as differential diagnostic considerations." (PMID 29701169, 2018). "The stem cell epitope CD34 is highly expressed in gangliogliomas." (PMID 22389832, 2011). "Given the working hypothesis that gangliogliomas arise from neuroectodermal neural precursor-like cells, neoplastic cells were next interrogated for individual neuroectodermal markers in addition to CD34." (PMID 36966348, 2023). "Histological investigation of the nervous tissue component from case #5 found elevated cellular density with presence of clusters of ChromoA-positive CD34-negative ganglion cells and alignments of oligo-like cells, evoking the histological features of a ganglioglioma." (PMID 30857565, 2019).
severe combined immunodeficiency (17 papers, 2011 to 2025). Severe combined immunodeficiency (SCID) comprises a group of rare monogenic primary immunodeficiency disorders characterized by a lack of functional peripheral T lymphocytes resulting in early-onset severe respiratory infections and failure to thrive. "Because M2-MFs can promote the expansion of HSCs, when co-cultured with hUCB CD34+ cells with M2-MFs, an increase in CD34+ cells and severe combined immunodeficiency (SCID) mouse-repopulating cells can be observed." (PMID 35629383, 2022). "CD34-positive cells from ADA-severe combined immunodeficiency patients transferred with the ADA gene with virus ex vivo are transplanted to refill ADA." (PMID 33425872, 2020). "We previously identified CD34-negative (CD34−) severe combined immunodeficiency (SCID)-repopulating cells as primitive hematopoietic stem cells (HSCs) in human cord blood." (PMID 29875383, 2018). "Indeed, these authors generated HTLV-1-infected humanized nonobese diabetic severe combined immunodeficiency (HU-NOD/SCID) mice by inoculating 4- to- 6-week NOD/SCID mice with human fetal liver-derived CD34+ cells infected ex vivo with HTLV-1." (PMID 21909275, 2011).
asthma (16 papers, 2006 to 2025). "Hematopoietic stem or progenitor cells (HSPCs) are for several reasons suggested to be involved in asthma and allergic diseases, e.g., in asthmatic patients CD34+ progenitor cells (HSPCs) were elevated in the sputum following exposure to an inhaled allergen." (PMID 40346984, 2025). "They found IL-5 and IL-13 producing CD34+ stem cells were present in the sputum of patients with asthma, and increased after allergen challenge." (PMID 36177009, 2022). "CD34+ fibrocytes were purified from peripheral blood of asthmatic (Global Initiative for Asthma treatment step 4–5) and normal subjects and cultured for 5∼7 days." (PMID 35547213, 2022). "In the severe asthma group the level of CD45+ CD34+CD11b+ cells correlated to decline in forced expiratory volume in 1 s (FEV1) (r = −0.68 p = 0.03)." (PMID 28720095, 2017). "Around 25% of fibroblasts-like cells in BAL fluid from asthma patients with basement membrane thickness express fibrocytes markers CD34 and α-SMA." (PMID 24822215, 2014). "Attenuation of SDF-1 receptor expression on the BM CD34+ cells together with reduction of SDF-1 levels in the BM was shown to regulate the release of progenitors from BM in allergen induced asthma." (PMID 24381572, 2013). "Cd34−/− animals also exhibited reduced tissue eosinophil recruitment in asthma and ulcerative colitis models and Cd34−/− eosinophils demonstrated a cell-intrinsic reduction in chemotaxis in vitro." (PMID 21494591, 2011). "Our findings support this paradigm and are consistent with prior reports in murine models of both asthma and bleomycin induced lung fibrosis showing that CD34+ is rapidly lost upon entry into diseased tissue." (PMID 21586112, 2011). "Others have shown that in bronchial biopsies from patients with mild asthma, cells expressing CD34, CD45 and α-SMA, consistent with fibrocytes, differentiated into myofibroblasts and resulted in increased thickness of the lamina reticularis." (PMID 21219601, 2011). "There were increased numbers of CD34 + Col I + cells and few CD34 + α-SMA + cells below the basement membrane in the bronchial mucosa of patients with asthma, and these cells increased significantly within 24 hours after exposure to allergen." (PMID 21219601, 2011). "These are cells of particular relevance to asthma and atopy, such as monocytes/macrophages, eosinophils, pregranulocytic CD34+ cells, neutrophils, and subsets of B lymphocytes and probably also T lymphocytes." (PMID 20003473, 2009). "The outgrowth of fibroblasts in BALF from a sub-group of patients with mild asthma indicate a possible origin from circulating fibroblast progenitor cells, due to their relative high expression of fibrocyte markers CD34, CD45RO and α-SMA." (PMID 16571120, 2006). "Asthma patients with detectable fibroblasts in bronchoalveolar lavage samples show a markedly thicker BM with an over 10-fold increase in CD34/CD45RO/α-SMA– and CD34/procollagen I–expressing cells, suggesting strong correlation between recruited fibrocytes and the BM thickness." (PMID 37655660, 2023). "Previous human studies have demonstrated that decreased TLR2 mRNA expression and receptor function due to SNPs in the TLR2 gene are positively associated with asthma susceptibility, and high-atopic-risk infants have been reported to have low TLR2 expression on their cord blood CD34 (+) cells." (PMID 23781124, 2013). "Circulating CD34+ fibrocytes express CD45, collagen I, and α-smooth muscle actin, and have been suggested to be precursors of bronchial myofibroblasts in asthma." (PMID 35670856, 2022). "This is the first study to report an increased number of fibrocytes expressing CD34/CD45RO/α-SMA/procollagen I, and a localization of these cells to areas close to the basement membrane in steroid-naive patients with mild asthma when compared to controls." (PMID 16571120, 2006).
asthma (continued). "In the combined group of RA, severe asthma, ILD and RA-ILD patients, the level of cultured fibrocytes and CD45+ CD34+CD11b+ cells was significantly higher in the patients with normal C-reactive protein (CRP) (<10 mg/L) than in patients with elevated CRP (both p = 0.001)." (PMID 28720095, 2017). "A possible role of hematopoietic progenitor cells in establishing cellular inflammation in allergic diseases such as rhinitis, asthma or eczema was described in a pilot study showing increased CD34+ cell traffic in those patients as compared to non-allergic controls." (PMID 39890627, 2025).